MET (MET proto-oncogene, receptor tyrosine kinase)
Diseases named in the same sentence as MET in open-access papers (continued):
Sharing a sentence is not in itself a finding about the gene and the disease.
cancer (continued). "Cancer stage may be an important factor that contributes to MET staining as late-stage cancer is generally characterized by MET overexpression and surgical specimens are usually obtained from early-stage patients, whereas biopsies are more commonly obtained from late-stage patients." (PMID 34557411, 2021). "Moreover, upstream of both RAF and PI3′-kinase signaling are the large family of receptor tyrosine kinases, such as EGFR, MET, ROS, ALK, and NTRK, that are mutated in a wide range of different cancers and for which there are numerous FDA-approved drugs linked to predictive biomarkers." (PMID 34298710, 2021). "Finally, we revealed that a c-MET inhibitor (CZT) could inhibit the cancer cells’ proliferative and metastatic capacities induced by the DNM3 depletion." (PMID 34490234, 2021). "Therefore, although the HGF/c-MET pathway, immune cell infiltration and immune pathway scores integrated in this study can satisfy the prediction of 11 cancers, it is difficult to find a feature that could be widely used in all cancers." (PMID 34261467, 2021). "We conclude that MET expression could be used as a prognostic tool in HGSC, but measures of stemness should be taken into consideration when further evaluating the mechanism/s underlying the driving effect of this receptor tyrosine kinase in cancer." (PMID 34069138, 2021). "Therefore, specific binding of rilotumumab to HGF neutralizes the interaction between HGF and c-MET and inhibits c-MET phosphorylation and downstream signaling, resulting in inhibition of cancer cell proliferation, survival, and invasion through partial antagonism of c-MET phosphorylation." (PMID 33466394, 2021). "Therefore, inhibiting MET has been attractive therapeutically in several cancer types." (PMID 33568750, 2021). "Thus, the absence of metastasis in the triple therapy group may be partially due to the loss of cancer cells (secondary to the cytotoxic effect of gemcitabine) and the decreased stemness of the surviving cells due to HGF/c-MET inhibition." (PMID 32203220, 2020). "However because all the patients were papillary type 2, we did not detect MET mutations in pRCC patients in the pan-cancer analysis, which are more important driver mutation of type 1 pRCC than type 2 pRCC." (PMID 32811483, 2020). "However, only sub-groups of patients with these cancers can hope to benefit from MET inhibitors." (PMID 33149187, 2020). "There is evidence that c-MET expression may be associated with expression of immunoregulatory molecules such as programmed cell death ligand (PD-L1) and Indoleamine-2,3-dixoygenase (IDO) in cancer cells." (PMID 32117721, 2020). "However, MET is amplified and/or mutated and/or HGF is overexpressed in cancers." (PMID 32549194, 2020). "However, we were able to assess the effects of HGF/c-MET inhibition on cancer cell invasion." (PMID 32203220, 2020). "The HGF levels in cancer tissue are not simply associated with pMET because only tcHGF—but not scHGF, which exists at much higher levels than tcHGF—is a key molecule for the activation of MET." (PMID 33121208, 2020). "Therefore, the antitumour effects of compound 12c could not only result from MET activation but also other targeted proteins/kinases in these cancer cell lines." (PMID 31137515, 2019). "Besides, quercetin could inhibit the activities of many kinases implicated in cancer cell biology, such as ABL1, Aurora-A, -B, -C, CLK1, FLT3, JAK3, and MET." (PMID 31998395, 2019). "Interestingly, our panel included genes already described to be cancer predisposition genes (FAS, ITK, KIF1B, PGR and MET) or previously reported as playing important roles in cancer (ABI1, ARID5B, DNMT3A, HEY1, KDM5C, NCOA1, NUP98, and SLC34A2), or in DNA repair process (FANCF)." (PMID 30925779, 2019). "Thus, MET may be an effective therapeutic target in combination therapy with PD-1/PD-L1 blockade, based on its pro-tumorigenic and immune suppressive role in cancer." (PMID 31480591, 2019).
cancer (continued). "More specifically, the c-Met-mutated iPSC organoid technology that we describe, could be also a major experimental platform for testing the efficiency of novel and future MET inhibitors in cancer therapy." (PMID 31575031, 2019). "Thus, the ability of SEMA3C to simultaneously transactivate multiple RTKs such as EGFR, HER2 and MET could facilitate the switch of primary dependency of cancer growth from one RTK pathway to another." (PMID 30759745, 2019). "In our study we proposed a model of the paradoxical functions of nMET in cancer cell death for clearance of mislocalized MET to sustain membrane MET function, and meanwhile, for survival, cancer stem cells may be the driver for aggressively evolved cancer through cancer stemness and differentiation." (PMID 30700325, 2019). "In conclusion, analogously to findings pertaining to inhibition of ErbB2 family of receptors, MET inhibition also seems to modulate glucose metabolism and this observation could potentially serve as a mean to predict cancer cells responses to MET targeting-based treatments." (PMID 29455660, 2018). "However, the efficacy of MET inhibitors remains undocumented in other types of cancer." (PMID 30208970, 2018). "Upon binding of HGF to MET, the kinase domain phosphorylates growth factor receptor-bound protein 2 (GRB2) and GRB2-associated binding protein 1 (GAB1) and activates diverse downstream signaling pathways important in cancer, including the ERK/MAPK, PI3K-Akt/PKB, Crk-Rap, and Rac-Pak pathways." (PMID 29866143, 2018). "Therefore, studying c-MET expression represents a promising approach for targeted cancer therapy." (PMID 29899871, 2018). "Therefore, c-MET inhibitor (CBT-101) co-treatment may improve responses to cancer immunotherapy in settings beyond c-MET- dependent tumors." (PMID 30400835, 2018). "Thus, the suppression of HGF/c-MET pathway in cancer cells may also contribute to the antitumor effects of deguelin through modulating the angiogenesis activity of human endothelial cells." (PMID 29416603, 2018). "Thus, MET dysregulation may participate in the lymph node metastasis process of SCLC through the transcriptional misregulation in cancer pathway." (PMID 30364292, 2018). "Taken together with the data obtained using H3122/CR-1 cells in this study, MET activation in cancer progression might be a common phenomenon to render cancer cells more malignant, especially with respect to aspects of metastasis, without affecting the response to drugs." (PMID 28938595, 2017). "Interestingly, c-MET inhibition as a single agent and in all other combinations exerted a pro-apoptotic effect which is in keeping with similar published reports in other cancers." (PMID 29100344, 2017). "Indeed, c-MET is activated in a variety of cancers, such as renal, ovarian, and lung." (PMID 28485003, 2017). "Additionally, EGFR, HER2, c-MYC, and MET have been identified to be potential biomarkers that predict the efficacy of the pharmacological treatments targeted against protein products of these genes in various cancers." (PMID 28764718, 2017). "Furthermore, disseminated cancer cells may undergo metastatic colonization via an MET‐independent pathway." (PMID 28548345, 2017). "However, improper activation of c-MET may confer proliferative and invasive/metastatic abilities of cancer cells." (PMID 29104726, 2017). "However, responsive cancer cells invariably develop resistance to MET-targeted treatment." (PMID 28968967, 2017). "Consequently, c-MET has become a leading target candidate for cancer therapy." (PMID 28404966, 2017). "Although the participation of key canonical pathways, such as those involving PI3K-Akt, MAPK, IGF, FGF, MET and mTOR, is well established in different cancers, these pathways cannot capture the complex and context-dependent cellular rewiring patterns behind distinct cancer phenotypes." (PMID 27527857, 2016). "Therefore, c-MET shows high potential as a therapeutic target for human cancer." (PMID 27187326, 2016).
cancer (continued). "Since other studies describe that the presence of vasoinvasive growth is significantly associated with cancer recurrence and poor prognosis of patients diagnosed with HNSSC, we hypothesize that the effect of MET staining pattern on survival is subservient to that of vasoinvasive growth." (PMID 26909606, 2016). "Moreover, we found decreased levels of p-c-MET in harvested cancer tissues compared with controls." (PMID 27917934, 2016). "Moreover, MET has been indicated as an attractive target for cancer therapy." (PMID 24416238, 2014). "Additionally, NK2, though its ability to antagonize HGF proliferation could be useful for anti-cancer therapy, however its partial activation of MET may also preclude this application." (PMID 28548073, 2014). "Thus, depending on the target system considered, MET activation may trigger detrimental responses (uncontrolled proliferation and tissue invasion in cancer) or beneficial effects (tissue and organ development, maintenance, and repair)." (PMID 28548076, 2014). "The functional interaction analyses in this study further strengthen the importance of Ets-1 in regulating cancer metastasis due to the pathway associations we have observed in WNT, vascular endothelial growth factor, and MMP signaling, as well as ERK5, MAPK, EGF, PDGF, MET and GPCR pathways." (PMID 24280356, 2013). "Moreover, c-MET may work with WNT or NOTCH pathways for the self renewal of cancer cells or stem cells." (PMID 22253909, 2012). "Interestingly, a similar variant of MET lacking the ectodomain but retaining the transmembrane and intracellular domains has been discovered in several cancer samples." (PMID 21114864, 2010). "PDAC cancer stem cell markers including CD44, MET, CD133, FUT4, ACVR1, mTOR, and KLF4 were positively related to IARS2 expression." (PMID 40092487, 2025). "Western blot analysis demonstrated that cancer serum induced 2.8-fold and 2.5-fold activation of IGF-1R and c-MET autophosphorylation, respectively, with corresponding downstream AKT phosphorylation." (PMID 40804939, 2025). "As a result, these cancer cells respond well to c-MET inhibitors, highlighting c-MET as a target for drug development." (PMID 40361420, 2025). "MET, another attractive RTK target for cancer treatment, is found predominantly in epithelial cells and is activated by its high‐affinity ligand, the hepatocyte growth factor (HGF)." (PMID 39980226, 2025). "Since taxanes are commonly used to treat other hormonally dependent cancers, we also analyzed the link between STMN1, HGF, MET, and STMN1/MET gene expression signatures and taxane treatment response in an mBC patient cohort using the ROCplot dataset on BC." (PMID 40723207, 2025). "The mRNA expression of cancer-related molecules, including those within the HGF/MET signaling pathway, were determined by microarray analysis, and compared between non-metastatic CRTC2 and metastatic CRTC2 (liver metastasis: CRTC2-LV)." (PMID 40076928, 2025). "Cabozantinib, a multikinase inhibitor targeting VEGFR2, c-MET, RET, and AXL, has shown efficacy in overcoming resistance to other therapies across various cancers." (PMID 39924521, 2025). "The results showed a decrease in the c-MET expression, which was mainly observed in regions containing GFP+ cancer cells, and a concurrent increase in HGF expression compared to the control group." (PMID 41289612, 2025). "TAS-115, as a multi-targeted kinase inhibitor, disrupts pro-survival signaling by blocking c-MET/HGF and VEGFR2 pathways, thereby attenuating downstream PI3K/Akt/mTOR activation and diminishing the ability of cancer cells to withstand stress." (PMID 41289612, 2025). "By underscoring the ISR-induced post-transcriptional modulation of MET, we unveil a detailed portrait of how ISR integrates into the MET-driven invasive growth programme of cancer cells." (PMID 39774381, 2025).
cancer (continued). "For example, EGFR- or MET-expressing cancer cells enhance glycolytic activity and lactate production, stimulating CAFs to secrete HGF via NF-κB, thereby activating MET signaling and driving TKI resistance." (PMID 40693266, 2025). "Among these shared targets, several key genes involved in cancer-related pathways were identified, including EGFR, PARP1, SRC, MET, GSK3B, and CYP19A1." (PMID 40963691, 2025). "This activation, in turn, triggers multiple intracellular phosphorylations of c-MET, VEGFR, and PDGFR, thereby altering downstream signaling cascades and ultimately promoting cancer cell proliferation, invasion, and metastasis." (PMID 41289612, 2025). "In colorectal cancer, NSD2 overexpression accelerates cell proliferation and migration by increasing global H3K36me2 levels and several cancer-promoting genes, such as ADAM9, EGFR, and MET." (PMID 41301842, 2025). "This distinct immune landscape highlights the crucial role of c-MET expression levels in shaping the TME and affecting the immune system’s ability to detect and destroy cancer cells." (PMID 40281554, 2025). "This matriptase-induced HGF/c-MET signaling constitutes a second wave of EGF signaling, promoting cancer cell scattering, migration, and invasion." (PMID 40361420, 2025). "Clinical studies report MET and HGF overexpression correlate with cancer progression and poor prognosis." (PMID 40723207, 2025). "On the one hand, the interesting gene list contains many cancer genes, such as ERBB2, HMGA1, and MET, that are related to these cancer types, which have been widely studied." (PMID 40139908, 2025). "MET and HGF genes can induce epithelial–mesenchymal transition (EMT) in ESCC, endowing cancer cells with stronger invasiveness and metastatic potential." (PMID 40244296, 2025). "Of interest, phosphorylation of MET and expression of HAI-1 were reciprocally observed in the majority of cancer tissues." (PMID 40299447, 2025). "Since the co-regulation of STMN1 with HGF and MET protein expression is indicative of a coordinated mechanism, the differential phosphorylation of STMN1 was evaluated to determine its impact on cancer progression and metastasis." (PMID 40723207, 2025). "Most notably, many of these early response alterations in the cancer cells are known pro‐angiogenic transcripts, including ITGA2, CLDN12, SMAD7, MET, KLF4, ID3 and ID1." (PMID 40116596, 2025). "The study’s preliminary results indicated that 49% ORR was achieved in patients with high MET amplification (defined as ≥10 gene copies in the FISH method) and/or high overexpression (defined as overexpression of MET on 90% of cancer cells in the IHC method)." (PMID 40002158, 2025). "Specifically, binding of HGF to MET induces potent MET phosphorylation and subsequent downstream activation of AKT and MAPK signaling pathways which positively drive cancer cell proliferation." (PMID 41368576, 2025). "GJB4 promotes cell proliferation and metastatic activities by activating the MET–AKT pathway and was suggested as a novel target for this deadly cancer." (PMID 41154660, 2025). "Several studies reported that LAMB3 overexpression is linked to cancer hallmarks, including cell proliferation, migration, invasion, and cancer progression via the PI3K/Akt signaling pathway, AKT-FOXO3/4, and c-MET/Akt signals." (PMID 38473784, 2024). "The key functional role as cytoplasmic chaperones is to regulate proteostasis by keeping substrate proteins (such as EGFR, MET, AKT, and many other kinases) in a folded and functional state, thus participating in human cancer development and progression." (PMID 39509399, 2024). "Emerging evidence suggests a significant crosstalk between c-MET and TGF-β pathways that contributes to immune evasion in cancer." (PMID 39664377, 2024). "Recent studies have reported that RTKs other than KIT, such as FLT3-ITD, PDGFRA, MET, and insulin-like growth factor receptor 1 (IGF-1R), also use the Golgi/TGN as their signaling platform in cancer cells." (PMID 38679330, 2024).
cancer (continued). "Targeting both c-MET and TGF-β pathways holds promise for enhancing the efficacy of cancer therapies and overcoming immune evasion." (PMID 39664377, 2024). "A research study demonstrated that the use of the c-MET inhibitor tivantinib resulted in an increase in PD-L1 expression in NSCLC cell lines, leading to evasion of T-cell-mediated killing by cancer cells." (PMID 39201787, 2024). "Through UALCAN analysis, high expression of FOXM1 or MET was related to shorter overall survival of UVM patients and higher cancer stages of UVM." (PMID 38342795, 2024). "Clinical trials have shown remarkable effectiveness in several cancers, particularly in NSCLC and other tumors carrying fusion ALK genes or amplified c-MET genes." (PMID 38397899, 2024). "MET phosphorylates ROR1, which is overexpressed in certain cancers, particularly B-cell malignancies." (PMID 39769452, 2024). "In summary, BsAbs targeting multiple receptors, such as c-MET, EGFR and immune cell receptors, offer a promising approach to cancer immunotherapy by leveraging immune cell cytotoxicity and restoring immune response function." (PMID 39664377, 2024). "The decrease in activated c-MET and CD44 levels following Gal-4 knockout indicates that Gal-4 plays a significant role in activating these pathways, promoting cancer cell proliferation and metastasis." (PMID 39664377, 2024). "Based on the responsiveness of highly selective c-MET inhibitors to c-MET overexpressing cancer, we believe that the reduced PFS in the c-MET+ CTC high group suggests the potential effectiveness of c-MET inhibitors in treating patients with HR+/HER2− mBC." (PMID 38238761, 2024). "By utilizing the ‘Specific RNA Transcripts’ function within the ‘Analyses’ section of FLIBase, we investigated the dysregulation of the receptor tyrosine kinase c-MET (MET) and its implications in cancer." (PMID 37697439, 2024). "mRNA expression of FAM83A, LY6D, MET, MUC16, MYEOV, and WNT7A were significantly elevated in cancer than healthy tissues (P<0.05)." (PMID 38169540, 2024). "Here, we chose MET, a tyrosine kinase receptor of HGF, as a treatment target because various cancers, including OC, are characterized by an alternating MET expression, which is generally associated with a poor prognosis and aggressive phenotypes." (PMID 38672564, 2024). "To determine the accuracy and LOD of amplifications, we tested reference materials with known copy numbers across six cancer driver genes (EGFR, ERBB2, FGFR3 MET, MYC and MYCN)." (PMID 39682116, 2024). "Targeting c-MET with inhibitors like cabozantinib, crizotinib, foretinib, PF04217903, and tivantinib disrupted antioxidant defenses, culminating in apoptotic cancer cell death." (PMID 39664377, 2024). "From a theoretical standpoint, the binding energy of cancer-related proteins with CBHQs and PIBHQs was found to be generally higher for kinases such as EGFR, MEK1, and c-MET, with ΔGbin values ranging from −11.4 to −8.5 kcal/mol." (PMID 39000394, 2024). "Capmatinib 9 is a highly selective c-MET inhibitor (IC50 = 0.13 nM), characterized by both in vitro and in vivo effectiveness vs. c-MET-activated preclinical cancer models." (PMID 38338677, 2024). "Further analysis revealed that Gal-4 interacts with c-MET and CD44 on the cell surface, facilitating cancer progression." (PMID 39664377, 2024). "Mesothelin (MSLN) promotes the level and activation of MET through the JNK signaling pathway, enabling cancer cells to disrupt tight junctions and the integrity of the blood-brain barrier (BBB), thus penetrating the barrier." (PMID 39712244, 2024). "Unlike the concept of “oncogene addiction,” where the oncogene is a primary driver, the inappropriate activation of MET leading to “oncogene expedience” is a result, rather than the cause, of the transformed phenotype, and may facilitate the cancer’s progression to metastatic spreading." (PMID 38675409, 2024).